SOX10 (SRY-box transcription factor 10)
Diseases named in the same sentence as SOX10 in open-access papers (continued):
Sharing a sentence is not in itself a finding about the gene and the disease.
melanoma (continued). "Quantitative analyses of SOX10 intensity according to ZEB1 expression level (high, intermediate, low and negative) confirmed a significant decrease in SOX10 levels when ZEB1 expression increases in melanoma cells." (PMID 38519642, 2024). "Remarkably, we found that A-485 does not significantly downregulate SOX10 mRNA levels in 9 of 10 melanoma cell lines tested, which was confirmed using alternative SOX10 primers." (PMID 38994683, 2024). "Our findings indicate that the presence of strong and diffuse TRPS1 expression may lean towards a diagnosis of AFX over angiosarcoma or melanoma, provided it is supported by other commonly used discriminatory immunohistochemical markers like ERG and SOX10." (PMID 39051323, 2024). "Overall, our results show a novel p300 and SOX10 regulatory axis and suggest that p300 KAT inhibition may confer anticancer effects to broad populations of melanoma cells, including those driven by SOX10 activation." (PMID 38994683, 2024). "Interestingly, while some ZEB1 peaks were conserved in MDA-MB-231, peaks in ZEB2, SOX10 and NGFR were only found in melanoma cells." (PMID 38519642, 2024). "Observing increased IFNγ-induced PD-L1 expression in the dedifferentiated 624Mel cells is partly in line with previous studies where SOX10 knockdown, which reduces MITF expression in melanoma cells, led to increased IFNγ-induced PD-L1 expression in three out of four tested melanoma cell lines." (PMID 39736644, 2024). "In addition, 67.7% (32/51) of melanoma cell lines in the CDM dataset possessed more than two copies of both EP300 and SOX10, and we labeled these lines as EP300/SOX10 co-amplified." (PMID 38994683, 2024). "Understanding the role of SOX10 and MITF in RTK regulation may disclose how treatment‐induced transcriptional reprogramming could be utilized in the optimization of melanoma treatment strategies." (PMID 36251678, 2023). "They included tumors displaying a biphasic appearance with conventional melanoma areas and dedifferentiated areas lacking expression of S100, SOX10, MelanA, and HMB45." (PMID 37373134, 2023). "Molecular studies of melanoma cells with absent SOX10 showed reduced expression of MITF, elevated expression of p21/WAF1 and p27KIP2, hypophosphorylated RB, and reduced levels of E2F1." (PMID 38132479, 2023). "In this respect, Fraga GR reported a similar case of a 75-year-old man with a similar lesion composed of conventional melanoma and a dedifferentiated area resembling atypical fibroxanthoma, with it being negative for MelanA and SOX10 but positive for CD10." (PMID 37373134, 2023). "EMPD is typical CK7-positive, CK20-positive or negative, p63-negative, SOX10-negative and CEA-positive unlike squamous cell carcinoma which is p63-positive and malignant melanoma which is SOX10-positive." (PMID 36766569, 2023). "Nevertheless, cases of desmoplastic melanomas lacking all conventional melanocytic markers, including S100 and SOX10, have been described." (PMID 37373134, 2023). "Although not related to a phenotype switch in the immune-competent melanoma mouse models used, Sox10 knock-out was also shown to reduce melanoma tumor growth in a T cell-dependent manner." (PMID 35432344, 2022). "We used this ratio since SOX10-negative/low cells often appear to be a subclonal population in melanoma patient samples." (PMID 35296667, 2022). "Accordingly, melanoma cells lacking SOX10 display gene enrichment in EMT programs, as well as in metabolism and microenvironment-related pathways such as hypoxia and glycolysis." (PMID 35912100, 2022).
melanoma (continued). "In order to discern the role of SOX10 in determining the aggressive phenotype of MITF-methylated melanoma, we specifically targeted SOX10 by CRISPR/Cas9 to generate a SOX10 knockout (SOX10KO) MITF-methylated melanoma cell line with SOX10-unmethylated promoter CpGs." (PMID 36040798, 2022). "SOX10 immunofluorescence analysis in A375 (BRAF V600E), MeWo (wild-type for BRAF and NRAS), and 1205Lu (BRAF V600E) melanoma cell lines showed a similar level of heterogeneity and confirmed the co-presence of SOX10-low and -high expressing cells in basal culture conditions." (PMID 35296667, 2022). "Finally, we subjected SOX10+ (MM383) and SOX10– (IGR-39) melanoma cell lines to increasing concentrations of BRAF inhibitor." (PMID 36040798, 2022). "Given the presence of SOX10-negative cells in pretreatment melanoma, we sought to characterize this subpopulation." (PMID 35296667, 2022). "The high number of pale or SOX10-negative tumor cells in lymph-node and distant organ metastases, led to an analysis of the red-color level (red chromaticity) in primary melanomas and melanoma metastases." (PMID 36361209, 2022). "The malignant melanoma component stained positive for SOX10 and Pan-melanoma markers and was negative for AE1/AE3." (PMID 35494985, 2022). "With the major advances of single-cell RNA sequencing, SOX10-negative melanoma cells have recently been detected among therapy-resistant tumors." (PMID 36040798, 2022). "Thus, for early-stage patients with a low immune score, the OS of melanoma patients with tumors of high SOX10 (Wald test, p = 0.0012) or MLANA (Wald test, p = 0.0051) was worse than that of those with low levels of SOX10 or MLANA." (PMID 35058553, 2022). "Since both SOX10 and MITF have fundamental roles in developing melanocytes and in melanoma progression, depletion of SOX10 in an MITFlo background resulted in high lethality for most of the melanoma cell cultures tested." (PMID 36040798, 2022). "Here, we hypothesized that SOX10 could transcriptionally modulate SMARCA4 expression and maintain melanoma cell proliferation." (PMID 36317703, 2022). "In conclusion, melanoma cells lacking the melanocyte transcription factor MITF can be divided based on SOX10 mRNA levels." (PMID 36040798, 2022). "Importantly, expression of SOX10, DEPDC1B, and SCUBE3 are positively correlated with microvessel density in the advanced stage of melanomas." (PMID 35088579, 2022). "The IHC profile of these tumors shows positivity for a range of markers: S100 (nuclear marker; sensitive for melanoma), SRY-box transcription factor 10 (SOX10; nuclear marker; highly specific for melanoma), human melanoma black 45 (HMB45; cytoplasmic marker), and Melan-A (cytoplasmic marker)." (PMID 36289768, 2022). "Further supporting a role for a NCP in melanoma, regulatory elements near neural crest genes, such as sox10, are activated in melanoma cell lines and NCCs, but not generally in other adult tissues or a range of cancer cell lines." (PMID 34099848, 2021). "In addition, FTO level was found to be increased in human melanoma, knockdown of which increases m6A methylation in PD-1, CXCR4, and SOX10, leading to increased RNA decay through the m6A reader YTHDF2." (PMID 33611339, 2021). "The 15 negative conventional pan-melanoma-cocktail cases were represented by 9 cases with SOX11/SOX10/MITF triple positivity, 4 cases expressing only SOX10 positivity, and 2 cases that expressed HMB-45 and melan-A." (PMID 33801642, 2021). "Triple MITF/SOX10/SOX11 co-expression was seen in 9 out of 15 negative conventional pan-melanoma-cocktail cases." (PMID 33801642, 2021). "Additionally, induction of PITX1 strongly suppressed SOX10 expression and SAMMSON transcription, which act as oncogenic driver genes in melanoma, via up-regulation of SOX9." (PMID 34526609, 2021).
melanoma (continued). "To further elucidate the inhibitory mechanism, we investigated the effect of VP on the SRY (sex determining region Y)-box 10 (SOX10) and paired box gene 3 (PAX3) transcription factors that regulate melanoma markers such as protein melan-A (MART-1) and MITF expressed in melanoma cells." (PMID 33672928, 2021). "HMB-45, SOX10, and tyrosinase, but not melan-A, proved to differentiate the nevi from malignant melanomas successfully, with high specificity." (PMID 34206844, 2021). "Interestingly, the expression of SAMMSON, which is known as a melanoma-specific long non-coding RNA that is regulated by SOX1024, coincided with a reduction in SOX10." (PMID 34526609, 2021). "As the two members of the pan-melanoma cocktail, HMB-45 and tyrosinase, proved to differentiate benign vs. malignant lesions, together with SOX10, the present paper suggests that, in the conventional cocktail, melan-A should be substituted by SOX10, for a better differentiation." (PMID 33801642, 2021). "Intriguingly, while some NCSC factors, such as SOX10 and YY1, are activated upon melanoma formation and are required for melanoma growth, other NCSC-associated factors, such as CD271/NGFR/p75NTR, PAX3, and FOXD3 promote melanoma cell invasiveness and metastasis formation." (PMID 34417458, 2021). "Another example of the role of SOX10 in melanoma is the finding that ERK phosphorylates and regulates SOX10 sumoylation at lysine 55, which is required for the regulation of its transcriptional activity and target selection in BRAF-mutant melanoma." (PMID 33024276, 2020). "siRNA silencing of SOX10 may contribute to the G1 phase arrest of melanoma cells via inhibiting the expression of cyclin/cyclin-dependent kinases (CDK) complex, suggesting the antineoplastic effects of SOX10 knockdown." (PMID 33344444, 2020). "We have established a connection between SOX10 and the WNT/β-catenin signaling pathway by identifying β-catenin as a direct protein-protein interaction partner of SOX10 in an unbiased MS-based approach in melanoma." (PMID 32238882, 2020). "In addition, expression of SOX10 and melanoma inhibitory activity (MIA) are tightly correlated in melanoma cell lines." (PMID 33344444, 2020). "SOX10 binds and interacts with MITF or other pro-differentiation transcription factors, thereby promoting the development of melanoma." (PMID 33344444, 2020). "The melanin-laden cells were negative for two melanoma markers: the cytoplasmatic staining of Melan-A and the nuclear staining of SOX10." (PMID 32957691, 2020). "Here, we show that MEK and RAF inhibitors do not suppress levels of SOX10 protein in patient-derived cells in vitro, as well as in melanoma patients in vivo." (PMID 32238882, 2020). "MITF and SOX10 suppress expression of DIRC3, which potentially contributes to melanoma development." (PMID 33329688, 2020). "Our study is the first to demonstrate the protein-mediated regulation of the SOX10-WNT axis in melanoma biology, shedding light on the molecular mechanism of SOX10 regulation and resolving the controversy around the role of canonical WNT signaling in melanoma." (PMID 32238882, 2020). "SOX10 predominantly occupies distal (non-promoter) enhancer regions in melanocyte and melanoma genomes, colocalizes with MITF at enhancers, and interacts with BRG1 at melanocyte-specific enhancer regions." (PMID 31399133, 2019). "Consistently we found that IFNγ downregulates FTO in melanoma cells, and FTO mediates resistance to melanoma cell killing by IFNγ through its m6A demethylase activity and downstream targets PD-1 (PDCD-1), CXCR4, and SOX10." (PMID 31239444, 2019). "Immunofluorescence staining showed that NEDD9 was localized in the cytoplasm and co-expressed with most, if not all, of SOX10+ pigmented nevus and primary melanomas, whereas SOX9 was barely detectable." (PMID 30642390, 2019).
melanoma (continued). "The discrepancies between the different studies could be attributed to melanoma heterogeneity with distinct expression levels of SOX9 and/or SOX10 in the tumors." (PMID 30642390, 2019). "Since FTO promotes melanoma tumorigenicity and regulates the expression of tumor-promoting melanoma cell-intrinsic PD-1 as well as CXCR4 and SOX10, we reasoned that FTO may also regulate the response of melanoma to immunotherapy." (PMID 31239444, 2019). "In contrast, SOX9 expression began to express in a subset of NEDD9+ melanoma cells, which had metastasized to the small intestine and another subset of NEDD9+ cells exhibited SOX10 expression, whereas we detected co-expression of SOX10, SOX9, and NEDD9 in another patient with intestinal melanomas." (PMID 30642390, 2019). "Indeed a decrease in the level of Ubiquitin Ligase RNF125 has been described to correlate with SOX10/MITF expression and to promote BRAF inhibitors resistance in melanoma." (PMID 31118886, 2019). "The predominant association of SOX10 and NEDD9 but not SOX9 expression in melanoma specimens is further supported by co-expression of these two factors at different levels in a series of malignant melanoma cell lines." (PMID 30642390, 2019). "In contrast, SOX9 expression was significantly upregulated in SOX10 KD, consistent with previous observations that SOX10 normally suppressed SOX9 expression which otherwise would have elicited a pro-apoptotic response in melanoma cells." (PMID 30642390, 2019). "Although GFP expression was also occasionally detected in the dermis, none of the GFP+ dermal cells expressed melanocyte and/or melanoma markers, including Sox10, S100b, and Nestin 32–34." (PMID 31685822, 2019). "Indeed, SOX9 OE at the highest titer (200 μL) in both SOX10 KD A375M and WM266–4 melanoma cells significantly restored the levels of NEDD9 mRNA and protein expression of both parental and phosphorylated forms compared to SOX10 KD alone." (PMID 30642390, 2019). "In vitro functional studies further showed that NEDD9 KD caused a marked reduction of cell growth, invasive behavior and colony formation capacity as observed in SOX10 KD, suggesting that NEDD9 is required for proliferation, invasion and oncogenicity of melanoma cells." (PMID 30642390, 2019). "Interestingly, adult stem cells expressing NC markers SOX10 and CD271 were also reported to be present in human melanoma." (PMID 31118886, 2019). "Except for melanoma, this IHC marker can be expressed in just 12% of all breast carcinomas, and no SOX-10 can be detected in the carcinoma of lung, colon, endometrium, and ovary." (PMID 30383642, 2018). "Furthermore, IPA protein-protein interaction (PPI) analysis for co-module #12 showed that melanoma-related transcription factors, such as MITF, PAX3, SOX8, and SOX10, formed a sub-network." (PMID 29950679, 2018). "Intra-assay reproducibility and quantification was accomplished by manually staining 5 serial sections from three different tissue types (tonsil, melanoma, NSCLC) with one set for each of the UltiMapper PD-1 (CD3, CD45RO, PD-1, CK/Sox10) and PD-L1 (CD8, CD68, PD-L1, CK/Sox10) I/O kits." (PMID 30400835, 2018). "Notably, a positive correlation was also found between SOX10 and FOXD3 in both data sets when analyzing all melanoma genotypes and selectively BRAF mutant melanoma." (PMID 29295999, 2018). "Consistently, we find that knockdown of SOX10, the upstream regulator of FOXD3 also sensitizes mutant BRAF melanoma cells to Vemurafenib in vitro and in vivo, suggesting that SOX10 can protect melanoma cells against the acute cytotoxic effect of RAF inhibitors." (PMID 29295999, 2018). "Therefore, SOX10 not only exerts a cytoprotective role against RAF inhibitors, but also participates in the regulation of melanoma cell growth." (PMID 29295999, 2018).
melanoma (continued). "Other specific IHC markers can be used to distinguish metastases from less common primary sites, including renal cell carcinoma (CK7−, CD10+, RCC+), cervical carcinoma (p16+, ER−, PR, and positive HPV status), and malignant melanoma (S-100, MART-1, HMB-45, and SOX10)." (PMID 28730323, 2017). "In addition to SOX10, SOX2—another member of the HMG-box transcription factor family—also plays an important role in the control of self-renewal and tumorigenicity of melanoma-initiating cells." (PMID 29156643, 2017). "Thus, we performed functional assays to validate our in silico predictions in human melanoma cells and investigated the expression signatures of MITF, SOX5 and SOX10 in respect to clinically relevant parameters." (PMID 26927636, 2016). "We have chosen not to use SOX10 in the present work because other authors suggest that S100 is a very sensitive marker for melanoma cells." (PMID 27087056, 2016). "It is of course possible that other signaling pathways play a role in neural crest cells fate regulation and thus upstream of Sox10 could regulate GSN expression during embryonic development and formation of melanocytes and melanoma in adult organisms." (PMID 25352156, 2016). "Furthermore, we wanted to confirm computationally that SOX5 and SOX10 are regulators of MITF expression in melanoma cells and thus analyzed a dataset of melanoma cells only." (PMID 26927636, 2016). "Besides SOX10, we identified SOX5 regulating MITF in human melanoma cells and validated its inhibitory effect experimentally by functional and reporter assays." (PMID 26927636, 2016). "Interestingly, the prediction of Breslow thickness using all of the investigated regulators (SOX5, SOX10, and MITF) showed good prediction performance only for thin melanoma tumors (<1 mm) and was rather poor for thick melanomas." (PMID 26927636, 2016). "We propose that this is not the case in melanocytic cells and that SOX9, unlike SOX10, is neither required for normal melanocyte stem cell homeostasis nor for formation of congenital nevi and primary melanoma." (PMID 25629959, 2015). "SOX-10 has been shown to be a sensitive marker for cutaneous melanoma and is highly specific to distinguish melanoma from its non-melanocytic mimickers, such as excision scar, atypical fibroxanthoma and dermatofibrosarcoma protuberans." (PMID 26316887, 2015). "SOX10, MITF, and JUN were significantly regulated in melanomas in comparison with cancer." (PMID 26044366, 2015). "To gain insight into the possible interplay between SOX10 and SOX9 during tumor progression, we quantified the expression levels of SOX10 and SOX9 in normal human melanocytes, in cells from giant congenital naevi, and in a melanoma cell line (M010817;) using quantitative RT-PCR analysis." (PMID 25629959, 2015). "Sox10 haploinsufficiency in mice can lead to tumour regression in an already established nevus, and in zebrafish, turning off MITF activity in an established melanoma leads to rapid tumour regression." (PMID 25670789, 2015). "Having identified anti-SOX10 and anti-SOX9 specific antibodies, we reveal virtually exclusive expression patterns of these transcription factors in the normal human skin and in a large set of melanoma biopsies and cell lines." (PMID 25629959, 2015). "Next, we addressed whether the cross-regulation between SOX10 and SOX9 is functionally relevant in human melanoma cells." (PMID 25629959, 2015). "SOX10 is a lineage‐specific transcription factor that strongly activates the MITF promoter, and is crucial for MITF expression; accordingly, it is required for melanoma cell survival." (PMID 25818589, 2015). "ATF2 control of melanoma development is mediated, in part, through its negative regulation of SOX10 and consequently, of MITF transcription." (PMID 24743024, 2014).